SEC14L1 (SEC14 like lipid binding 1)
Description:
May play a role in innate immunity by inhibiting the antiviral RIG-I signaling pathway. In this pathway, functions as a negative regulator of RIGI, the cytoplasmic sensor of viral nucleic acids. Prevents the interaction of RIGI with MAVS/IPS1, an important step in signal propagation. May also regulate the SLC18A3 and SLC5A7 cholinergic transporters.
Synonyms: SEC14L; PRELID4A
Tractability: PROTAC: ubiquitination databases record sites on it; its protein half-life has been measured.
Gene: Protein-coding gene on chromosome 17 (77,088,749 to 77,217,101, forward strand). Ensembl gene ENSG00000129657.
Subcellular location: Cytoplasm; Golgi apparatus
Subcellular location (Human Protein Atlas): Cytosol; Nucleoplasm
Gene Ontology:
Molecular function: protein binding; protein sequestering activity; RIG-I binding
Biological process: choline transport; negative regulation of cytoplasmic pattern recognition receptor signaling pathway; negative regulation of RIG-I signaling pathway
Cellular component: cytoplasm; cytosol; Golgi apparatus
Genetic constraint (gnomAD): Loss-of-function variants: 44 observed, 77.92 expected, observed/expected ratio (o/e) 0.56, 90% interval 0.44 to 0.73. The upper end of that interval is the gene's LOEUF score, 0.73, which puts it in group 2 of 6, group 1 being the genes least tolerant of losing a copy. Missense variants: 655 observed, 922.15 expected, observed/expected ratio (o/e) 0.71, 90% interval 0.67 to 0.76. Synonymous variants: 381 observed, 355.22 expected, observed/expected ratio (o/e) 1.07, 90% interval 0.99 to 1.17.
Homologues: Orthologues: chimpanzee SEC14L1 (99% identical), macaque SEC14L1 (99% identical), dog SEC14L1 (96% identical), guinea pig SEC14L1 (95% identical), rat Sec14l1 (95% identical), mouse Sec14l1 (95% identical), pig SEC14L1 (91% identical), tropical clawed frog sec14l5 (87% identical), zebrafish SEC14L1 (69% identical), Caenorhabditis elegans F28H7.8 (14% identical), Drosophila melanogaster CG13893 (13% identical), Caenorhabditis elegans ctg-1 (13% identical), and 1 more. Paralogues in human: SEC14L5 (67% identical), SEC14L4 (19% identical), SEC14L2 (18% identical), SEC14L3 (18% identical), SEC14L6 (17% identical), TTPA (10% identical).
Diseases named in the same sentence as SEC14L1 in open-access papers:
SEC14L1 is named in the same sentence as 17 diseases in open-access papers, as found by Europe PMC text mining. Sharing a sentence is not in itself a finding about the gene and the disease. The quoted sentences say what the papers report.
breast carcinoma (2 papers, 2022 to 2023). "High expression of SEC14L1 is significantly associated with lymphovascular invasion in breast cancer patients, where transcript abundance correlates positively with higher grade lymph node metastasis, and poor prognostic outcome." (PMID 35281034, 2022). "In addition, SEC14L1 affects innate immune processes by negatively regulating RIG-I-mediated antiviral signaling and is involved in the immune process of some diseases, such as lymphovascular invasion in breast cancer." (PMID 37035673, 2023).
COVID-19 (2 papers, 2022 to 2024). A disease caused by infection with severe acute respiratory syndrome coronavirus 2. "SEC14L1 is anti-inflammatory, which is significantly downregulated in COVID-19 patients." (PMID 38666857, 2024). "Besides PARP9, the three genes KRT8, SEC14L1, and ALCAM have also been linked to COVID-19." (PMID 38666857, 2024). "Neutrophil transcripts which are robustly expressed in the uninfected state, including anti-proliferation and pro-apoptotic genes (LST1, G0S2, CPPED1, BTG2, PMAIP1) and anti-inflammatory genes (AMPD2, SEC14L1, ZFP36), are significantly downregulated in COVID-19 patients." (PMID 36466858, 2022).
prostate carcinoma (2 papers, 2017 to 2022). A carcinoma that arises from epithelial cells of the prostate gland. "Its overexpression is also frequent in prostate cancer where SEC14L1 has been identified as a potential biomarker of aggressive progression of the disease." (PMID 35281034, 2022). "Another study found SEC14L1 to be overexpressed in prostate cancer." (PMID 28362259, 2017).
asthma (1 paper, 2024). "The findings demonstrate that CDC167, POSTN, SEC14L1, and SERPINB2 exhibit potential as diagnostic markers and therapeutic targets for individuals with asthma." (PMID 38580753, 2024). "However, the functional roles of CCDC167 and SEC14L1 in the context of asthma have yet to be fully elucidated." (PMID 38580753, 2024). "The expression of hub genes, including CCDC167, POSTN, SEC14L1, and SERPINB2, was significantly lower in healthy donors (controls) compared to asthma patients." (PMID 38580753, 2024). "The predictive value of the hub genes was assessed using ROC curves, and the aero under curves for CCDC167, POSTN, SEC14L1, and SERPINB2 were approximately 0.79, 0.87, 0.86, and 0.89, respectively, supporting their sensitivity and specificity in asthma diagnosis." (PMID 38580753, 2024). "Finally, CCDC167, POSTN, SEC14L1, and SERPINB2 were designated as the asthma hub genes because they were characterized by all three machine learning algorithms." (PMID 38580753, 2024).
dementia (1 paper, 2026). Loss of intellectual abilities interfering with an individual's social and occupational functions. "Variants on the SEC14L1 gene on chromosome 17 were also significant in the dementia-adjusted analysis." (PMID 41286463, 2026).
Intellectual disability (1 paper, 2015). "Transcriptome sequencing on lymphocyte messenger RNA from patients with intellectual disability (MIM 604167), harbouring mutant CTCF, and healthy individuals identified SEC14L1 as the top-ranked dysregulated gene in patients." (PMID 25716334, 2015).
lung adenocarcinoma (1 paper, 2011). A carcinoma that arises from the lung and is characterized by the presence of malignant glandular epithelial cells. "These genes, except SEC14L1, are primarily co-dominant in the classes 4, 1 and 2, i.e., squamous cell carcinomas (SQ), lung adenocarcinomas (Adeno) and normal lung (Normal)." (PMID 21909426, 2011).
mental disorder (1 paper, 2022). A disease that has its basis in the disruption of mental process. "Eight genes are implicated in viral (SEC14L1, JMJD6, SRSF2, TMPRSS2, MX1, MX2) or bacterial (COL8A1, SPIRE1) infections, seven genes (MFSD11, METTL23, CTTNBP2, BACE2, IMPA2, MPPE1 and GNAL) are involved in mental disorders and one gene (MGAT5B) is related to the Golgi complex." (PMID 35581286, 2022).
ovarian carcinoma (1 paper, 2021). A malignant neoplasm originating from the surface ovarian epithelium. "SEC14L1 with 3 alternatively spliced exons spanning exon 11 was specifically expressed in human peripheral blood leukocytes, and different protein isoforms may show differential expression in breast and ovarian cancer development." (PMID 34722250, 2021).
cancer (3 papers, 2011 to 2021). A tumor composed of atypical neoplastic, often pleomorphic cells that invade other tissues. "The 3’ UTR of SEC14L1 spans 3052 bps and contains 31 mutations from 27 samples distributed across 10 different cancer types." (PMID 28362259, 2017). "Although little is known about SEC14L1 in cancer, one study hypothesized that altered expression of the gene could contribute to breast tumorigenesis." (PMID 28362259, 2017). "VAMP8 is involved in calcium-dependent exocytosis process and SEC14L1 is a membrane trafficking protein, and none of them is linked to cancer pathways." (PMID 21909426, 2011).
neurological disorders (1 paper, 2022). "Indeed, identified genes are implicated in viral (SEC14L1, JMJD6, SRSF2, TMPRSS2, MX1, MX2) bacterial (COL8A1, SPIRE1), and neurological disorders (MFSD11, METTL23, CTTNBP2, BACE2, IMPA2, MPPE1 and GNAL), or in the functions of the Golgi complex (MGAT5B), organelle where viral envelope is occurred." (PMID 35581286, 2022).
SEC14L1 also shares sentences with these, for which no sentence is quoted: chronic lung disease (1 paper); lung carcinoma (1); lymph node metastasis (1); psoriasis (1); squamous cell carcinoma (1); tumor (1).